SRSF1 (serine and arginine rich splicing factor 1)
Diseases named in the same sentence as SRSF1 in open-access papers (continued):
Sharing a sentence is not in itself a finding about the gene and the disease.
systemic lupus erythematosus (10 papers, 2015 to 2025). An autoimmune multi-organ disease typically associated with vasculopathy and autoantibody production. "It has been noted that low levels of CD3ζ protein correlates with low levels of SRSF1 and development of the systemic autoimmune disease Systemic Lupus Erythematosus (SLE)." (PMID 26703587, 2015). "In patients with systemic lupus erythematosus, a low abundance of SRSF1 and an increase in proinflammatory cytokine have been linked observed and overexpression of SRSF1 could reverse this phenotype and rescue the hyperactivated T cell state." (PMID 40759740, 2025). "Other splicing factors of the same family, such as SRSF1, were shown to be essential for Treg homeostasis and activity, as observed in systemic lupus erythematosus patients, but also for regulation of inflammatory responses in macrophages and of antiviral responses." (PMID 41065049, 2025). "SRSF1‐mediated production of type I IFNs also prevents the development of systemic lupus erythematosus (SLE) by restraining T‐cell activation and is required for neuro‐immune suppression of the human neurotropic JC virus (JCV)." (PMID 34779563, 2021). "A recent report showed that SRSF1 enhances IL-2 production in T cells from systemic lupus erythematosus (SLE) patients." (PMID 25658361, 2015). "SRSF1 dysfunction leads to systemic lupus erythematosus (SLE) and psoriasis." (PMID 38302461, 2024). "Interestingly, T cells from patients with SLE (systemic lupus erythematosus) showed increased ubiquitylation of SRSF1 when compared to those from healthy individuals." (PMID 26273603, 2015).
breast tumors (9 papers, 2008 to 2024). "Splicing factor SRSF1 is an associated gene binding motif that matches with KER_37, which is upregulated in human breast tumors, and its overexpression promotes transformation of mammary cells." (PMID 31703384, 2019). "In breast tumors, PRMT1 overexpression is associated with increased SRSF1 arginine methylation and aberrant exon inclusion, which are critical for breast cancer cell growth in vivo and in vitro." (PMID 39201539, 2024). "SRSF1 is upregulated in human breast tumors, and its overexpression promotes the transformation of mammary cells." (PMID 35368030, 2022). "On the other hand, the splicing factor SRSF1 has been observed to be upregulated in breast tumors acting as an oncogene by producing impaired splicing isoforms of the pro-apoptotic genes BCL2 Like 11 (BIM) and the Bridging integrator 1 (BIN1) which are involved in the tumoral phenotype." (PMID 32635183, 2020). "PRMT1-mediated SRSF1 methylation is important in regulating alternative splicing of genes that are known to be oncogenic, such as AURKA and RAD1, both highly expressed in breast tumor samples." (PMID 39201539, 2024). "For example, in breast tumour cells with similar cellular environments to the MCF-7 cells, the knockdown of SRSF1 may provide a powerful way of inducing apoptosis, as there is both a switch in splicing and a reduction in translation of Mcl-1L protein." (PMID 23284704, 2012). "Analysis by immunohistochemistry of the expression of hnRNP A1, hnRNPH, RBM9/FOX2, SRSF1/ASF/SF2, SRSF2/SC35, SRSF3/SRp20, SRSF7/9G8 in breast tumors shows that the expression of hnRNP A1, but not the other tested RBPs, is associated with metastatic relapse." (PMID 26930004, 2016).
lung adenocarcinoma (7 papers, 2012 to 2022). A carcinoma that arises from the lung and is characterized by the presence of malignant glandular epithelial cells. "In human lung adenocarcinoma cell lines, SRSF1 overexpression lead to EMT, with the loss of epithelial markers (e.g., E-Cadherin) along with the acquisition of mesenchymal markers (e.g., vimentin, fibronectin, and N-cadherin)." (PMID 30012957, 2018). "Particularly in lung adenocarcinoma, high expression of SRSF1 is associated with the presence of metastases, a more aggressive phenotype, and chemotherapy resistance." (PMID 30012957, 2018). "In particular, in lung adenocarcinoma, SRSF1 overexpression is associated with a more aggressive phenotype, the presence of metastases, and chemotherapy resistance." (PMID 28806747, 2017). "SRSF1 and GSK3B were filtered through “overall survival”, and high expression was associated with a poorer prognosis than low expression in a subset of lung adenocarcinoma patients." (PMID 36523489, 2022). "In the first dataset, the splicing factor SRSF1 was knocked-down using siRNA on the A549 lung adenocarcinoma cell line." (PMID 31238884, 2019). "The data set contains A549 lung adenocarcinoma cell lines which were treated with either scrambled RNA (SCR) or transfected with a siRNA that targets SRSF1." (PMID 29844567, 2018). "The performance of the developed algorithms was tested in an experiment where the splicing factor SRSF1 was knocked down using siRNA on the A549 lung adenocarcinoma cell line." (PMID 27315794, 2016). "Taken together, these results demonstrate that SRSF1 protein is overexpressed in a vast majority of NSCLC compared to normal lung tissues and is associated with criteria of tumor invasiveness in lung adenocarcinoma." (PMID 23071587, 2012). "Recently, Montuenga’s group reported that SRSF1 is overexpressed in lung adenocarcinoma in which it controls the expression of survivin, an anti-apoptotic protein." (PMID 23071587, 2012). "Therefore, it would be of interest to explore and concomitantly correlate miR-9, SRSF1 and MALAT-1 expression in lung adenocarcinoma metastatic cells and in primary tumors, and also to correlate their levels with EMT markers and lamin A expression." (PMID 28806747, 2017). "In this study, by using immunohistochemistry, we demonstrate that the SR proteins SRSF1 and SRSF2 are overexpressed in 63% and 65% of lung adenocarcinoma (ADC) as well as in 68% and 91% of squamous cell lung carcinoma (SCC), respectively, compared to normal lung epithelial cells." (PMID 23071587, 2012). "Taken together, these results demonstrate that SRSF1 overexpression promotes a more aggressive phenotype in lung adenocarcinoma but not in lung squamous carcinoma cell lines." (PMID 23071587, 2012).
neuroblastoma (7 papers, 2020 to 2025). Neuroblastoma (NB) is the most common solid, extracranial childhood tumor. "The elevated production of miR-10a and miR-10b in retinoic acid-induced neuroblastoma cells can inhibit SRSF1, which in turn promotes the final differentiation of neuroblastoma cells." (PMID 40032844, 2025). "In neuroblastoma cells, alcohol exposure reduced protein levels of serine/arginine-rich splicing factor 1 (SRSF1) and shifted the alternative splicing of the MCL1 antiapoptotic protein towards the shorter isoform (Mcl-1S) over the long isoform (Mcl-1L)." (PMID 38396082, 2024). "As predicted, SRSF1 levels decreased in neuroblastoma cells after retinoic acid treatment, which presumably altered the alternative RNA splicing of other mRNA transcripts." (PMID 34769047, 2021). "The relationship between miRNA regulation on SRSF1 expression and alternative RNA splicing has also been studied in neuroblastoma cells." (PMID 34769047, 2021). "In addition to these effects, ECM stiffness plays a role in controlling VEGF165 secretion and neuroblastoma angiogenesis through the YAP-RUNX2-serine-arginine-rich splicing factor 1 (SRSF1) axis." (PMID 39849659, 2025). "Also, retinoic acid-induced miR-10a and miR-10b upregulation in neuroblastoma cells, and subsequent repression of SRSF1, putatively results in terminal differentiation of neuroblastoma cells." (PMID 34196950, 2022). "For example, in neuroblastoma, both miR-10a and miR-10b degrade SRSF1 mRNA through complete complementation with its 3’UTR and downregulate the translation of SRSF1 as a result of decreasing SRSF1-mediated AS, thus inhibiting the migration, invasion, and metastasis of neuroblastoma cells." (PMID 33407694, 2021).
osteosarcoma (7 papers, 2020 to 2025). A usually aggressive malignant bone-forming mesenchymal neoplasm, predominantly affecting adolescents and young adults. "We analyzed RNA sequences obtained from downregulated SRSF1 in human U2OS osteosarcoma cell lines to explore the underlying mechanisms." (PMID 38735973, 2024). "We identified 6 splicing factor genes associated with the prognosis of osteosarcoma patients, namely SRSF1, SRSF4, SRSF5, SRSF7, SRSF8, and SRSF10." (PMID 39286028, 2024). "We note that SRSF1 was upregulated in osteosarcoma cell lines, such as U-2 OS, that expresses high levels of RIF1-L." (PMID 41489901, 2025). "As a whole, our findings indicate that increasing SRSF1 boosts the proliferation, migration, and invasive capabilities of osteosarcoma cells and decreases cell apoptosis in vitro." (PMID 38735973, 2024). "Subsequently, we first evaluated numerous phenotypes after elevating SRSF1 levels in U2OS human osteosarcoma cell lines." (PMID 38735973, 2024). "Through these splicing events, SRSF1 enhances tumor cell invasiveness and drug resistance, further driving the progression of osteosarcoma." (PMID 39497723, 2024). "Altogether, the heatmap showed genes that were upregulated and downregulated in osteosarcoma tissues, implying a high expression state of SRSF1 and potential pathogenicity." (PMID 38735973, 2024). "To determine the impact of SRSF1 on osteosarcoma development, we initially measured SRSF1 mRNA levels in four osteosarcoma cell lines and bone marrow mesenchymal stem cells." (PMID 38735973, 2024). "Here are some examples of how the splicing process affects osteosarcoma: Serine/Arginine-rich Splicing Factor 1 (SRSF1) is an important splicing factor that has been found to be closely associated with the progression of osteosarcoma when highly expressed." (PMID 39497723, 2024). "In all, our findings indicate that silencing SRSF1 appeared to hinder the proliferation, migration, and invasive capabilities of osteosarcoma cells and increase cell apoptosis in vitro." (PMID 38735973, 2024). "In this study, we investigated the expression and functional role of SRSF1 in osteosarcoma (OS)." (PMID 38735973, 2024). "On the other hand, chromatin immunoprecipitation assays showed that E2 binds a region comprised between nucleotides 565-363 upstream the SRSF1 AUG starting site through its N-terminal domain and transactivates the SRSF1 expression in the U2OS human osteosarcoma cell line." (PMID 32596243, 2020). "This study primarily demonstrated that reduced expression of MALAT1 leads to an increased binding affinity between SRSF1 and pre-mRNA (B-MYB and CENPE), thereby regulating alternative splicing mechanisms in osteosarcoma cells." (PMID 41019082, 2025). "However, the precise role of SRSF1 in osteosarcoma (OS) remains unclear." (PMID 38735973, 2024). "Specifically, studies have shown that SRSF1 influences the migration, invasion, proliferation, and apoptosis of osteosarcoma cells, while SRSF3 regulates ILF3 RNA splicing to control osteosarcoma growth." (PMID 39286028, 2024). "Lnc-KASRT serves as a potential treatment target via regulating SRSF1-related KLF6 alternative splicing and following P21/CCND1 pathway in osteosarcoma." (PMID 34568030, 2021). "In conclusion, lnc-KASRT serves as a potential treatment target by regulating SRSF1-related KLF6 alternative splicing and the P21/CCND1 pathway in osteosarcoma." (PMID 34568030, 2021). "Considering the effect of lnc-KASRT on SRSF1 and KLF6 alternative splicing, we further explored the role of KLF6-SV1 in osteosarcoma malignant behaviors and whether it would affect the function of lnc-KASRT." (PMID 34568030, 2021). "Furthermore, lnc-KASRT overexpression increased KLF6-SV1, MMP1, and MMP9 expression and decreased SRSF1 and KLF6-WT expression in osteosarcoma mice, but lnc-KASRT downregulation showed the opposite trend." (PMID 34568030, 2021).
osteosarcoma (continued). "This visual summary shows that lnc-KASRT located on SRSF1, interacts with SRSF1, then regulates alternative splicing of KLF6 to promote KLF6-SV1 coding while inhibiting KLF6-WT coding, and subsequently modifies P21/CCND1 pathway, finally leading to increased growth and invasion of osteosarcoma." (PMID 34568030, 2021).
ovarian carcinoma (7 papers, 2013 to 2025). A malignant neoplasm originating from the surface ovarian epithelium. "For example, CRNDE inducing cisplatin resistance through SRSF1/TIA1 signaling pathway in ovarian cancer." (PMID 40176901, 2025). "For example, LARP1, an RNA binding protein in ovarian cancer, is a post-transcriptional regulator of survival and tumorigenesis; RNA binding proteins SRSF1 and SRSF9 can promote Wnt signaling-mediated tumorigenesis by enhancing β-catenin biosynthesis." (PMID 32219019, 2020). "Moreover, lncRNA CRNDE increased SRSF1 expression and subsequently elevated TIA1 expression, which caused cisplatin resistance in ovarian cancer." (PMID 36105363, 2022). "Therefore, selectively targeting hnRNPLL, SRSF1, and SRSF6 may usher in an important new era of ovarian cancer treatment." (PMID 34244494, 2021).
melanoma (6 papers, 2017 to 2026). A malignant, usually aggressive tumor composed of atypical, neoplastic melanocytes. "Blocking the pro-angiogenic VEGF-Axxx isoform by inhibiting SRSF1 phosphorylation by SRPK1 inhibitors has been shown to reduce melanoma proliferation." (PMID 33807778, 2021). "Furthermore, pro-angiogenic expression of VEGF-A in melanoma is activated by SRSF1, a pre-mRNA splicing factor, through phosphorylation of SRPK1." (PMID 33807778, 2021). "SR splicing factor 1 (SRSF1) is an oncoprotein that positively regulates circMYC expression, potentially affecting melanoma cells." (PMID 38462618, 2024). "Finally, SRSF1 from tumor cells was expressed higher in HCC non-PD-1 respond group than in respond group, as validated in other cancers, including melanoma and basal cell carcinoma." (PMID 39837814, 2025).
renal cell carcinoma (6 papers, 2021 to 2024). "circ_000829 acts as an anticancer agent in renal cell carcinoma via inhibiting SRSF1-mediated selective splicing of SLC39A14." (PMID 38581057, 2024). "SLC39A14 through Circ_000829 and SRSF1-mediated alternative splicing suppression, plays an anticancer role in renal cell carcinoma." (PMID 37978473, 2023). "In the previous study, miR-766-3p could suppress the progression of renal cell cancer by targeting SRSF1 directly." (PMID 38365721, 2024).
viral infection (6 papers, 2011 to 2022). "The findings of this study could shed light to the potential cause as to why patients with immune-mediated diseases who have low Srsf1 expression in their T lymphocytes maybe more susceptible to viral infections." (PMID 36189299, 2022). "This is the first time that SRSF1 is studied in the context of T cell responses against viral infection, including the role of SRSF1 in cell cycle progression and proliferation of T cells in an inflammatory microenvironment caused by a viral infection." (PMID 36189299, 2022). "In this work, we also explore a mechanistic pathway for the involvement of SRSF1 in viral infections." (PMID 36189299, 2022). "SRSF1 controls the transcriptomic landscape of T cells during viral infection through the regulation of proliferation, IFN signaling and MAPK signaling pathways." (PMID 36189299, 2022). "To better understand how SRSF1 affects the biological processes in the context of viral infection, we performed RNA sequencing of spleen T cells from WT and Srsf1-cKO mice on day 8 post LCMV infection." (PMID 36189299, 2022). "To evaluate the role of SRSF1 in the cell-mediated immune response in viral infection, we infected WT and Srsf1-cKO mice with the lymphocytic choriomeningitis virus (LCMV)-Armstrong strain in an acute infection model using established protocols." (PMID 36189299, 2022). "SRSF1 has also been associated with proliferative pathways in different types of cancer, which would condition the expansion of CD8 T lymphocytes in response to viral infection, pathways in which the p38 is also involved." (PMID 36189299, 2022). "Therefore, the differences shown here likely depend on the role of SRSF1 during activation of T lymphocytes after viral infection." (PMID 36189299, 2022). "SRSF1 is known to control the alternative splicing of a number of genes, which interconnect several signaling pathways, some of which are related to the T response in viral infections." (PMID 36189299, 2022). "Furthermore, SRSF1 is required for antigen-specific IFN-γ cytokine responses in a viral infection challenge in mice." (PMID 36189299, 2022). "To evaluate the role of SRSF1 in CD8 T cells in response to viral infection, we assessed the CD8 T cell populations in the LCMV-infected WT and Srsf1-cKO mice." (PMID 36189299, 2022). "One can postulate that SRSF1 is possibly induced and expressed during viral latency as well as early in the replication cycle of JCV as an innate host response to viral infection." (PMID 27257867, 2016).
acute myeloid leukemia (5 papers, 2021 to 2025). Acute myeloid leukemia (AML) is a group of neoplasms arising from precursor cells committed to the myeloid cell-line differentiation. "Conversely, PRMT5-catalyzed SDMA of SRSF1 was shown to control cassette-exon choice in acute myeloid leukemia, underscoring the conserved role of SRSF1 methylation across cancers." (PMID 40846633, 2025). "Among these, the mRNA expression of BUB3, DHX9, PRMT1, THOC4, THOC7, U2AF1, and ZNF207 (BUGZ) were found to increase in several primary tumors compared to healthy tissues, while SRSF1 (ASF/SF2) was downregulated in most cancers (except for acute myeloid leukemia—LAML)." (PMID 36553448, 2022). "The epigenetic alterations in SRSF1 are involved in the progression of acute myeloid leukemia (AML)." (PMID 39034387, 2024).
autoimmune disease (5 papers, 2022 to 2024). A disorder resulting from loss of function or tissue destruction of an organ or multiple organs, arising from humoral or cellular immune responses of the individual to their own tissue constituents. "Substantial evidence has shown that SRSF1 is involved in cancer, neurodegenerative disease, and autoimmune disease through the targeted regulation of the selective splicing of multiple genes." (PMID 39659162, 2024). "The splicing factor SRSF1 regulates the transcriptional program of Treg cells, and mice with aberrant SRSF1 activity develop autoimmune disorders." (PMID 37895245, 2023). "Reduced SRSF1 expression in T cells is correlated with autoimmune disease, hypersensitivity, and inflammation, and these phenotypes result in part from elevated mTOR activity." (PMID 35202654, 2022).
acute lymphoblastic leukemia (4 papers, 2012 to 2023). Leukemia with an acute onset, characterized by the presence of lymphoblasts in the bone marrow and the peripheral blood. "Upregulated SRSF1, with the cooperation of PRTM1, acts as an adverse factor in pediatric acute lymphoblastic leukemia." (PMID 37206090, 2023). "In childhood acute lymphoblastic leukemia SRSF1 was further found to be upregulated together with protein arginine methyltransferase PRMT1, which is involved in promoting SRSF1 nuclear localization." (PMID 26273603, 2015). "In pediatric acute lymphoblastic leukemia (ALL), SRSF1 was upregulated in clinical samples from de novo or relapsed patients and decreased when complete remission was achieved." (PMID 37206090, 2023).